IL6 (interleukin 6)
Diseases named in the same sentence as IL6 in open-access papers (continued):
Sharing a sentence is not in itself a finding about the gene and the disease.
infection (continued). "Meanwhile, both the inducing cytokines (TGF-β, IL-6, IL-23 and IL-21) and the inhibitory cytokines (IFN-γ and IL-4) of Th17 cell generation all increased after infection." (PMID 22102924, 2011). "In these studies determination of relative transcription of IL-6, TNF-α, or IL-17 genes was generally used as a measure of the immune response to infection." (PMID 21829346, 2011). "scSIV-LMP1 infection resulted in a significant increase in IL-1β, IL-6, IL-8, IL-10, IL-12p70 and TNF, while scSIV-LMP1-CD40 infection resulted in increase in IL-1β, IL-6, IL-8, IL-10 and TNF at various time points." (PMID 21592361, 2011). "Patients with PB disease present very low bacterial counts, exhibiting localized infection and lesions characterized by expression of type 1 (TH1) T helper lymphocyte-related cytokines (cell-mediated immunity) as IL-2, IL-6, IL-12, IFN-γ, and TNF." (PMID 22220182, 2011). "In lungs infected with H9N2 LPAI virus, IL-6, IL-1β and IFN-β mRNA was found to be induced after infection in different parts of the lungs." (PMID 21314972, 2011). "Further elevation of IL-6 and SAA was observed during long-term infection, and significant differences were observed in both wild-type and B6.Apoeshl mice." (PMID 21625524, 2011). "Myr+ recNef treatment of primary MDMs as well as infection of MDMs with nef espressing HIV-1 pseudotypes induces the synthesis and the release of several inflammatory cytokines and chemokines (i.e. IL-1β, IL-6, TNFα, MIP-1α and MIP-1β)." (PMID 21886773, 2011). "The highest levels of proinflammatory cytokines (IL-6, TNF-α and the murine IL-8 homologue KC) in blood and brain of the infected mice were observed after 6 h of infection." (PMID 21811575, 2011). "In the first, immune response genes such as IL-6, IL-1α, IL-1β and IFN-β were upregulated one hour following infection but this upregulation rapidly returned to baseline and was not sustained." (PMID 21789257, 2011). "Although levels of expression of CD58 (LFA3), an adhesion molecule, and the cytokine IL6 altered most rapidly following exposure to EBV, expression of CD58 on CD23+ cells was the earlier marker of infection with EBV." (PMID 21352549, 2011). "On the other hand, four days after infection, TLR3−/− mice showed significantly increased mRNA expression of IL-6, CCL2, CCL11 and IFN-λ." (PMID 21637773, 2011). "As expected, SeV infection induced much more IL6 in Mavs+/+ MEFs than in Mavs−/− MEFs, confirming the MAVS-dependent cytokine production in response to infection by a prototype RNA virus." (PMID 22110409, 2011). "PT also suppressed levels of IL-1β, IL-12, IFN-γ, IL-6, KC, MCP-1 and TNF-α in the airways after PR8 infection." (PMID 21533103, 2011). "Infections of horses with equine influenza virus elicited the production of inflammatory cytokines such as INF-α, IL-1β, IL-6, and TNF-α." (PMID 21592354, 2011). "Levels of the cytokine IL-6 and of the chemokines CXCL9, CXCL10, and CCL4 were significantly lower in vaginal washes one day after infection with HSV-2/gD compared with HSV-2/gD-Δ7-15." (PMID 21283640, 2011). "During VVΔE3L infection high levels of TNF-α, IFN-β, IFN-α, IL-6 and ISG15 mRNA were detected, which is in accordance with previous publications." (PMID 22174864, 2011). "Expressions of TLR3, IFNα, IL6, IL8 and CCL5 in the lungs following infection with the two HPAIVs were low." (PMID 21826229, 2011). "Twenty-four h after RV1B infection, CXCL1/KC, CXCL2/MIP-2, IL-6, CCL2/MCP-1 and IFN-γ expression in wild-type mice increased 3–5 fold." (PMID 21637773, 2011). "At 6 hours post-H5N1/2004 infection, there were marked increase in the expression of CXCL-10/IP-10 and CCL-5/RANTES (60-120 folds); while there were only relatively minor increase in IL-6 and IL-8 expression (2-10 folds)." (PMID 21108843, 2010). "The IL-6 released by KC after the activation of NFκB was shown to control HBV gene transcription and replication in hepatocytes shortly after infection." (PMID 21994686, 2010).
infection (continued). "In summary, at the late phase of infection (i.e. 18 and 24 hours post-infection), TNF-α, IL-6, IL-8, CCL-5/RANTES and CXCL-10/IP-10 mRNA remained at high levels for H5N1/2004 and H9N2/1997; which were in contrast to those observed for H1N1/2002." (PMID 21108843, 2010). "In active TB, macrophages release pro-inflammatory cytokines (IL-1, IL-6, TNF-α) in response to mycobacterial proteins and glycolipids, resulting in CD4 and CD8 T lymphocyte recruitment and activation at the site of infection and systemically." (PMID 20179751, 2010). "At day 5 post-infection, both MyD88−/− and TLR2−/− mice had reduced lung IL-6 concentrations when compared to WT mice." (PMID 21060793, 2010). "The expression profile of three key pro-inflammatory cytokines, namely IFN-γ, IL-6 and TNF-α, was monitored over the course of infection in the serum of animals infected with 107 or 104 PFU of D2Y98P." (PMID 20436920, 2010). "However, recent studies have revealed that some inflammatory markers such as the high-mobility group box-1 protein (HMGB1), the lipopolysaccharide-binding protein (LBP) and the Interleukin-6 (IL-6) may be detectable already in the early state of infection and bacteraemia." (PMID 20158885, 2010). "Secretion of cytokines IL-6, IL-8 and GM-CSF by RWPE-1 was measured 24 h and 48 h after infection with P. acnes." (PMID 20420679, 2010). "After 24 h, OppD-KO infection led to lesser amounts of TNF-α, IL-1β and IL-6 production in macrophages compared to the wild type." (PMID 20808924, 2010). "Our study showed that the detectable levels LBP, IL-6 and CRP differ in the earl stage of infection dependent on severity of infection." (PMID 20158885, 2010). "After 3 days of infection with MHV-68, both WT and TLR2−/− mice secreted similar IL-6 levels in the lung tissue, while MyD88−/− mice showed reduced IL-6 lung concentrations." (PMID 21060793, 2010). "A number of transcription factors were increased in expression following the infection, including CAAT/enhancer binding protein (also termed C/EBP or nuclear factor IL-6) which binds to promoters of APR proteins and IL-6 target genes." (PMID 20602791, 2010). "We therefore assessed the secretion of three key cytokines, IL-6, IL-8 and GM-CSF (also called CSF-2) from the prostate-derived epithelial cell-line RWPE-1 in response to infection with P. acnes." (PMID 20420679, 2010). "IL-6 and CXCL-10/IP-10 were induced in H9N2/1997 infections; but at relatively lower fold-changes than those of H5N1 throughout the time course examined." (PMID 21108843, 2010). "The amounts of IL-6 and IL-8 produced by DCs stimulated with poly(I:C), a TLR3 ligand, after infection with HHV-6 appeared to be significantly lower than those produced by mock-infected DCs." (PMID 20459723, 2010). "Macrophages harvested from TLR1−/− and TLR6−/− mice expressed TNF, IL-6, MCP-1, and IL-10 in response to LVS infection in vitro at comparable or higher levels than B6 mice." (PMID 19936231, 2009). "Infection with combinations of LLO-Lm-OVA and ActA-Lm-OVA led to the dose-dependent reduction of serum IFN-γ, IL-12p70, IL-6 and MCP-1 relative to ActA-Lm-OVA alone." (PMID 19730694, 2009). "Infection with HIV induces immune activation with high levels of circulating cytokines, such as tumor necrosis factor-alpha (TNF-α), interleukin-6 (IL-6), IL-10, and some chemokines." (PMID 19852800, 2009). "Compared to TNF and IL-1β, the secretion of IL-6 and MCP-1 by THP-1 cells infected with vMyxM013-KO virus was first detected much later, and these were only measurable after 12 hours post infection." (PMID 19851467, 2009). "This activation is probable due the greater expression of FT induced by TNF-α and IL-6 whose level in serum and BAL were singnificantly increased between 8 and 48 h post-infection." (PMID 19835595, 2009). "As with other APP, infection can increase the production of AGP through cytokines TNF α, IL-1 and IL-6." (PMID 20042096, 2009).
infection (continued). "In the vaccination model used here, however, there is a significant dampening of the infection-induced increase in IL-1β, TNF, IL-6 and iNOS, especially observable at peak parasitaemia." (PMID 19341445, 2009). "Previous studies show PIC infection of murine macrophages leads to NF-κB activation, and the production of TNF-α and IL-6." (PMID 19814828, 2009). "Specifically, the induction of inflammatory molecules such as TNF, IL-6, and MCP-1 by active MTb infection is important for inhibition of TB disease progression, while at the same time these same molecules enhance HIV-1 replication." (PMID 19568431, 2009). "After challenge with the pathogen, these cytokines increased significantly, reaching a peak between 8 h and 12 h post-infection with higher values of TNF-α and IL-6 in the L. casei group." (PMID 19835595, 2009). "We thus next examined the levels of TNF, IL-1β, IL-2, IL-6, IL-10, and MCP-1 (also known as CCL2) in human PBMC infected by CDC1551, HN878, and HN878 pks1-15::hyg 2 and 4 days post-MTb infection." (PMID 19568431, 2009). "rhodesiense-infected mice treated with cordycepin and deoxycoformycin starting 20 days after infection contained diminished levels of IFN-γ, IL-1β, IL-6 and TNF-α mRNA compared to untreated infected controls when measured 10 days after treatment." (PMID 19652702, 2009). "Here, we demonstrate that vMyxM013-KO infection of THP-1 cells also induces other cytokines and chemokines (TNF, IL-6, and MCP-1) that are regulated by the NF-κB pathway, in addition to the cytokines controlled by the caspase 1/inflammasome complex." (PMID 19851467, 2009). "Infection leads to the expression of inflammatory cytokines such as TNF-α, IL-1, and IL-6 as well as other factors such as FasL, heat shock proteins, reactive oxygen species, and nitric oxide, all of which are known to regulate caspase activation." (PMID 20069051, 2009). "All genes play major roles in immune response during infection including cytokines (IL8, IL6, IL10, IL1B, and TNF) and SAA3 (an acute-phase protein), as well as PMN adhesion selectin-L (SELL) and LYZ (involved in anti-microbial defense)." (PMID 19925655, 2009). "In mice infected with the ΔsigC mutant, the levels of TNF-α, IL-1β, IL-6 and IFN-γ began to drop 14 days post infection and persisted throughout the study while a significant reduction in CCL-2 and CCL-5 levels was detected 70 days after infection." (PMID 18798983, 2008). "IL-6 and TNF-α are proinflammatory cytokines that regulate innate immunity physiologic host defense processes during infection, airway damage in COPD, and acute lung injury." (PMID 19057703, 2008). "Upon infection with pYV+ the bacterial burden was higher at all investigated time points than in ΔyopH infected IFN-γR-/-, IL-6-/- or wild type mice." (PMID 18803824, 2008). "At 72 h after infection TNFα levels remained lower in MyD88 KO mice, while MCP-1 and IL-6 levels tended to be higher in these animals." (PMID 18946505, 2008). "Four days post-infection with the PR8 virus, CD4+ T cells in the lungs of both H17-memory and naïve WT and IL-6−/− mice were enumerated by flow cytometry." (PMID 18389078, 2008). "TNFα and IL6 levels were lower in TLR2 KO mice than in WT mice, especially at 72 h after infection (p < 0.05 and p < 0.001, respectively)." (PMID 17676990, 2007). "IL-6 and MCP-1 showed marked increases by day 4 after infection; and MIP-1α and MIP-1β exhibited moderate increases on day 4, coinciding with gene expression data." (PMID 17725815, 2007). "A variety of cytokines and chemokines were measurable during infection including: GRO, IL-1β, IL-6, IL-10, IL-12, GM-CSF, TNFα, MDC, and IL-8." (PMID 17257430, 2007). "Many studies have evaluated the usefulness of various markers of infection in different septic conditions – C-reactive protein (CRP), procalcitonin (PCT), TNFα, and IL-6, IL-8, and IL-10." (PMID 17598889, 2007).
infection (continued). "On the other hand, we proposed that the prominent production of IL-10 from the early stages of the experimental HPAI infection was the compensatory response to overproduction of proinflammatory cytokines such as TNF-α, IL-6 and IL-12." (PMID 17662125, 2007). "The NNIS score and the evolution of serum IL-6 and various acute-phase proteins (C-reactive protein [CRP], albumin, prealbumin and transferrin) were correlated with postoperative infections and length of hospital stay (LOS)." (PMID 17505683, 2007). "Many authors target finding proinflammatory markers of infection and SIRS other than the CRP, such as PCT, IL-1, IL-6, or TNFα." (PMID 17598889, 2007). "The amount of IP-10 and IL-6 secreted by bronchial and alveolar epithelial cells infected with all three H5N1 viruses at 24 hours post infection were significantly higher (p < 0.01) than that secreted by cells infected with H1N1 virus." (PMID 16283933, 2005). "The cytokines secreted by phagocytes in response to infection include TNF-α, IL-1β, IL-6, IL-8 and IL-10." (PMID 16280065, 2005). "The cytokines secreted by phagocytes in response to infection include tumor necrosis factor (TNF)-α, IL-1β, IL-6, IL-8 as well as IL-10." (PMID 16280065, 2005). "Notably, interleukin-6 (IL-6) is a known inducer of STAT3 phosphorylation and has been implicated in maintaining B. abortus persistence in macrophages, but whether IL-6 intersects with other regulatory mechanisms of STAT3 during infection requires clarification." (PMID 41486271, 2026). "Levels of inflammatory cytokines IL‐1β, IL‐6, IL‐8, IL‐10, IL‐12/23p40, TNF‐α, and HMGB1 were significantly upregulated by infection with S. Typhimurium in the LT2 group." (PMID 41474380, 2026). "Specifically, fever‐induced HSP70/90 drives macrophage adaptation, T‐cell migration, and Th17 differentiation, whereas IL‐1β/IL‐6/TNF‐α enhances lymphocyte adhesion, Th1‐polarized and leukocyte exhibits promising clinical potential in oncology and infection control." (PMID 41298282, 2026). "However, on day 7 post-infection, levels of the pro-inflammatory cytokines TNF-α, IL-6, and IL-17A significantly decreased." (PMID 41236498, 2026). "Additionally, we observe elevated levels of specific cytokines, including IL-17, IL-6, IL-1β, and TNF-α, which collectively contribute to inflammation and tissue damage in the lungs during infection." (PMID 41597746, 2026). "Compared to primary infections, secondary infections exhibited significantly higher levels of five cytokines/chemokines: MIP‐1α, MIP‐1β, TNF‐α, IL‐6, and RANTES, highlighting that cytokine expression profiles can differentiate primary and secondary infections in early stages (within 24 h)." (PMID 41488232, 2026). "In our view, what governs clinical outcome is not merely the magnitude of IL‐6 elevation, but the host’s ability to enact an appropriate ‘braking’ response‐reducing IL‐6 levels once the initial infection has been addressed." (PMID 41488232, 2026). "However, in piglets, infection elicited substantial increases in serum inflammatory cytokines (TNF-α, IFN-γ, IL-6, and IL-10) but produced only mild clinical signs and limited pulmonary inflammation." (PMID 41971018, 2026). "Consequently, a type I interferon along with pro-inflammatory cytokines (IL-6 and TNF-α) that are produced to suppress viral replication and recruit immune cells to the infection." (PMID 41602762, 2026). "The LC group was characterized by persistent immune activation and proinflammatory responses for more than 180 days after initial infection compared with convalescent controls, including upregulation of JAK-STAT, interleukin-6, complement, metabolism and T cell exhaustion pathways." (PMID 41388153, 2026).
infection (continued). "Rather, severe infection is characterized by early interferon (IFN) imbalance followed by NF-κB-dominant inflammatory amplification, promoting sustained IL-6/JAK-STAT3 and MAPK signaling, chronic cytokine production, metabolic reprogramming, and impaired antitumor immune surveillance." (PMID 41893791, 2026). "During infection, pro-inflammatory cytokines (e.g., TNF-α, IL-6) are upregulated." (PMID 41602759, 2026). "For assessing the cytokine response, negative correlations were observed (Spearman test) between pre-infection levels of pro-inflammatory cytokines (IL-1β, TNF-α, IL-6) and viral loads in the moment of sacrifice in multiple organs, including the brain, lungs, and heart." (PMID 40969767, 2025). "Certain immune cells within vulnerable populations may generate TNF-α in response to external conditions and infection, IL-1β, IFN-α and IL-6, thereby promoting the production of IL-23 by dendritic cells." (PMID 40540498, 2025). "The upregulation of IL1B upon infection was absent in male mice, while the IL6 levels were higher relative to those in uninfected male mice, although significantly lower compared to those in the infected female group." (PMID 40143355, 2025). "Additionally, the mRNA expression level of IL-6 and IL-8 were also increased in A549 cells after rgDV2-NS1-K272R infection." (PMID 39972477, 2025). "PwCF have higher baseline levels of neutrophil recruitment factors including IL-6, IL-8, and TNF-α, leading to an increase in neutrophil recruitment with disputes on whether this occurs prior to infection or after the first infection." (PMID 40357395, 2025). "Neuroinflammation may be an outcome of infection with one or both organisms as observed by increased levels of CCL2 and IL-6 leading to AD pathogenesis." (PMID 40584180, 2025). "Although the precise mechanisms underlying CHIKV-induced AIN remain incompletely understood, existing evidence implicates an excessive inflammatory response, particularly the upregulation of pro-inflammatory cytokines such as IL-1β, IL-6 and TNF-α during the acute phase of infection." (PMID 40766840, 2025). "In addition, to assess the expression of inflammatory factors during the infection of Ras264.7 macrophages with WT BCG, BCG::ΔmfpA, pMV361-mfpA/BCG::ΔmfpA, and pMV261-mfpA::BCG, we measured the levels of TNF-α and IL-6 in the cell culture supernatants." (PMID 40558494, 2025). "Gene expression of interleukin (IL)-6, IL-8, TLR2, TLR4, IL-1 alpha (IL-1α), and CXCR1 was evaluated by quantitative real-time polymerase chain reaction at 0, 6, 12, 24, 48, and 72 h post-infection." (PMID 40453956, 2025). "Infection with MHV-68 resulted in an elevated abundance of cytokines (TNF-α and IL-6) that triggered inflammation, an upsurge in pyroptosis-related molecules involving caspase-1, IL-1β, and IL-18, along with a decrease in IL-10 concentration, an anti-inflammatory cytokine, in peritoneal macrophages." (PMID 40041420, 2025). "Early in infection, SARS-CoV-2 may transiently suppress the production of IL-6 and other pro-inflammatory cytokines in specific cell types, such as T cells, as part of its immune evasion strategy." (PMID 39940645, 2025). "For IL-6 and CXCL1/KC, the difference was more significant at 24 h post-infection." (PMID 40818988, 2025). "The combination of IL-1β, IL-8 and IL-6 showed high AUC values, indicating a high predictive accuracy to identify febrile UTI, which would be of interest to localize infection to the urinary tract when diagnosing a child with fever of unknown origin." (PMID 40856487, 2025). "Likewise, cytokines and chemokines including CRP, IL-15, IL-6, IP-10, MCP-1, TARC, MIP-1α, and IL-12p40 were increased following infection with WE-CL13-GP181M-185W-492I." (PMID 41086811, 2025).